HMCN1 (hemicentin 1)
Diseases named in the same sentence as HMCN1 in open-access papers (continued):
Sharing a sentence is not in itself a finding about the gene and the disease.
tumor (continued). "We next evaluated the association of the HMCN1 VAF with individual clinical characteristics (lymph node status, tumor grade, tumor size, and age) in the 64 tumor samples, which were divided into three groups by lymph node status: N0, N1, and N2–N3." (PMID 30279964, 2018). "Following this, we conducted predictive screening for HMCN1-specific drugs with tumor sensitivity." (PMID 41458588, 2025). "Detection via GSVA and the z-score-based algorithm confirmed that HMCN1 expression was positively correlated with pro-tumor processes such as EMT, angiogenesis, invasion, and metastasis, while simultaneously confirming its negative correlation with cell cycle activity." (PMID 41458588, 2025). "Our preliminary findings suggest that HMCN1 might drive tumor progression primarily by promoting the EMT process rather than directly regulating cell proliferation." (PMID 41458588, 2025). "Emerging evidence indicates an active role for HMCN1 in tumor progression." (PMID 41458588, 2025). "In the tumor of patient #1, we detected mutations in tumor suppressor genes such as MYO18B and CTNN2 and in genes related to adhesion, invasiveness, and survival (e.g., CDH23, HMCN1, and OBSCN) in samples collected at the resistance that were not present initially." (PMID 37620318, 2023). "Combining tumor-normal and inter-tumor analyses, we identified overexpressed targets including PDGFRB, FGFR4, ERBB2/3, CDK6 kinases and MFAP5, HMCN1, and Hsp proteins in HCC, many of which showed low frequencies of genomic and/or transcriptomic aberrations." (PMID 35433463, 2022). "This indicates that the HMCN1-high TME is not one of effective anti-tumor immunity, but rather a state of T-cell dysfunction and exhaustion, which facilitates immune evasion and explains the associated poor outcomes." (PMID 41458588, 2025). "Other genes such as KL, MNX1, HMCN1 and ADCY10 suggest that anoikis resistance is not restricted to survival pathways but also extends to metabolic and proliferative mechanisms that drive both tumour aggressiveness and treatment resistance." (PMID 40830065, 2025).
infection (1 paper, 2023). The state of being infected such as from the introduction of a foreign agent such as serum, vaccine, antigenic substance or organism. "These are involved in smooth-muscle function (FGFR1, GATA5 and STIM1), tissue organization (ADAMTS10), alveolar and epithelial function (ABCA3 and CLDN18), and inflammation and immune response to infection (CFH, CYTL1, HMCN1, LRBA and STIM1)." (PMID 36914875, 2023).
HMCN1 also shares sentences with these, for which no sentence is quoted: clear cell renal carcinoma (2 papers); Ewing sarcoma (2); myocardial ischemia (2); aortic aneurysm (1); aortic atherosclerosis (1); cardiac hypertrophy (1); cholangiocarcinoma (1); diabetes (1); endocervical adenocarcinoma (1); epidermolysis bullosa simplex (1); fibromatosis (1); fibrosis (1); gallstones (1); glomerular disease (1); head and neck cancer (1); head and neck squamous cell carcinoma (1); heart failure (1); infarction (1); insulinoma (1); keratoconus (1); kidney disease (1); liver cancer (1); lung carcinoma (1); mood disorder (1); Myocardial fibrosis (1); neurologic disorders (1); ovarian serous cystadenocarcinoma (1); prostate carcinoma (1); Sjogren syndrome (1); skin cutaneous melanoma (1).
A further 6 diseases each share a sentence with HMCN1 in 1 paper.